GPR37L1 (G protein-coupled receptor 37 like 1)
Description:
G protein-coupled receptor. Has been shown to bind the neuroprotective and glioprotective factor prosaposin (PSAP), leading to endocytosis followed by an ERK phosphorylation cascade. However, other studies have shown that prosaposin does not increase activity. It has been suggested that GPR37L1 is a constitutively active receptor which signals through the guanine nucleotide-binding protein G(s) subunit alpha. Participates in the regulation of postnatal cerebellar development by modulating the Shh pathway (By similarity). Regulates baseline blood pressure in females and protects against cardiovascular stress in males (By similarity). Mediates inhibition of astrocyte glutamate transporters and reduction in neuronal N-methyl-D-aspartate receptor activity (By similarity).
Synonyms: ETBR-LP-2; ETBRLP2; ET(B)R-LP-2
Tractability: Small molecule: it belongs to a druggable protein family. Antibody: UniProt places it where antibodies can reach, with high confidence; its Gene Ontology location is reachable by antibodies, with high confidence; UniProt predicts a signal peptide or a membrane-spanning region. PROTAC: UniProt records ubiquitination sites on it.
Target class: Family A G protein-coupled receptor; Short peptide receptor (family A GPCR); Membrane receptor; Peptide receptor (family A GPCR); Endothelin receptor
Gene: Protein-coding gene on chromosome 1 (202,122,886 to 202,133,592, forward strand). Ensembl gene ENSG00000170075.
Subcellular location: Cell membrane; Cell projection, cilium membrane
Subcellular location (Human Protein Atlas): Cell Junctions; Nucleoplasm; Plasma membrane; Vesicles
Pathways (Reactome):
Signal Transduction: G alpha (i) signalling events; Peptide ligand-binding receptors
Gene Ontology:
Molecular function: G protein-coupled peptide receptor activity; G protein-coupled receptor activity; peptide binding; prosaposin receptor activity; protein binding
Biological process: adenylate cyclase-inhibiting G protein-coupled receptor signaling pathway; positive regulation of MAPK cascade; cellular response to reactive oxygen species; negative regulation of systemic arterial blood pressure; G protein-coupled receptor signaling pathway
Cellular component: plasma membrane; receptor complex; membrane; ciliary membrane
Genetic constraint (gnomAD): Loss-of-function variants: 18 observed, 18.15 expected, observed/expected ratio (o/e) 0.99, 90% interval 0.68 to 1.47. The upper end of that interval is the gene's LOEUF score, 1.47, which puts it in group 6 of 6, group 1 being the genes least tolerant of losing a copy. Missense variants: 554 observed, 637.31 expected, observed/expected ratio (o/e) 0.87, 90% interval 0.81 to 0.93. Synonymous variants: 255 observed, 283.52 expected, observed/expected ratio (o/e) 0.9, 90% interval 0.81 to 1.
Homologues: Orthologues: chimpanzee GPR37L1 (99% identical), macaque GPR37L1 (95% identical), rat Gpr37l1 (92% identical), mouse Gpr37l1 (91% identical), guinea pig GPR37L1 (89% identical), dog GPR37L1 (87% identical), pig GPR37L1 (78% identical), zebrafish gpr37l1b (49% identical), zebrafish gpr37l1a (48% identical), tropical clawed frog gpr37l1 (48% identical), Caenorhabditis elegans gnrr-5 (14% identical). Paralogues in human: GPR37 (43% identical), EDNRB (21% identical), EDNRA (18% identical), NMUR1 (17% identical), GRPR (16% identical), NMBR (16% identical), BRS3 (15% identical), NTSR1 (15% identical), GHSR (14% identical), TRHR (13% identical), NTSR2 (13% identical), MLNR (12% identical), and 3 more.
Diseases named in the same sentence as GPR37L1 in open-access papers:
GPR37L1 is named in the same sentence as 29 diseases in open-access papers, as found by Europe PMC text mining. Sharing a sentence is not in itself a finding about the gene and the disease. The quoted sentences say what the papers report.
Parkinson disease (5 papers, 2015 to 2024). A progressive degenerative disorder of the central nervous system characterized by loss of dopamine producing neurons in the substantia nigra and the presence of Lewy bodies in the substantia nigra and locus coeruleus. "GPR37 has been implicated in Parkinson's disease and parkinsonism, while GPR37L1 deletion leads to precocious cerebellar development and hypertension." (PMID 26696893, 2015). "Both orphan GPCRs are widely expressed in the brain, where GPR37 has received the most attention for its link to Parkinson’s disease and parkinsonism, while GPR37L1 deletion leads to precocious cerebellar development and hypertension." (PMID 26635605, 2015).
Hypertension (3 papers, 2015 to 2020). The presence of chronic increased pressure in the systemic arterial system. "GPR37L1 ablation was reported to cause hypertension and left ventricular hypertrophy, and thus, we sought to further define the role of GPR37L1 in blood pressure homeostasis." (PMID 29625592, 2018). "In addition, GPR37L1 itself is encoded within a renin blood pressure quantitative trait locus, specifically in a sub-region that promotes high blood pressure in rats." (PMID 33633567, 2020). "Indeed, there is evidence that genetic deletion of Gpr37l1 in mice may cause high blood pressure." (PMID 33633567, 2020). "If the phenotype can be confirmed, this work suggests that GPR37L1 agonists would be useful additional drugs for the treatment of hypertension." (PMID 26635605, 2015). "Regardless, GPR37 and GPR37L1 remain promising therapeutic targets for the treatment of neurodegeneration and hypertension, respectively, although many additional studies will be necessary to confirm the mechanisms and relevance of these receptors to disease." (PMID 26635605, 2015). "Thus, the present study suggests that GPR37L1 is a contributor to CNS cardiovascular control, and the sex differences therein, and may contribute to the role of the CNS in hypertension and heart failure." (PMID 29625592, 2018). "While GPR37L1 had previously been linked to hypertension, the animals’ sex was not reported." (PMID 29625592, 2018). "Furthermore, GPR37L1 KO mice had evidence of significant cardiac hypertrophy as measured by heart weight to body weight ratios, consistent with prolonged hypertension." (PMID 26635605, 2015). "In addition to these effects in the brain, GPR37L1 has a reported role in maintaining blood pressure homeostasis, and may represent a potential drug target for the treatment of hypertension." (PMID 33633567, 2020). "In mice, genetic ablation of Gpr37l1 causes sex-dependent effects; female mice lacking Gpr37l1 (GPR37L1−/−) have a modest but significant elevation in blood pressure, while male GPR37L1−/− mice are more susceptible to cardiovascular dysfunction following angiotensin II-induced hypertension." (PMID 33633567, 2020).
demyelinating disease (2 papers, 2025). A broad group of disorders that affect the myelin sheaths that cover the neurons. "It was demonstrated that one of the most drastically reduced proteins in the brains of Gpr37/Gpr37L1 double knockout mice was the myelin-associated glycoprotein MAG, suggesting that GPR37 may be a potential drug target for the treatment of demyelinating diseases such as multiple sclerosis." (PMID 40822851, 2025). "Future experiments may consider using the conditional knockout or pharmacological blockade of the Psap–Gpr37l1 pathway to verify its functional necessity in OPC replenishment and blood–brain barrier repair, offering translational insights into demyelinating diseases." (PMID 40563324, 2025).
depression (2 papers, 2022 to 2024). "Prosaptide is an agonist for both GPR37L1 and GPR37, yet only GPR37L1 was found in our study to be downregulated in brain regions of the depression model." (PMID 38670310, 2024). "Gpr37l1 was found to be significantly downregulated in HY (>1.5-fold, adjusted p < 0.01) and modestly downregulated in PFC and HIP of depression mice (>1.2-fold, adjusted p < 0.05) relative to control." (PMID 38670310, 2024).
glioblastoma (2 papers, 2020 to 2021). The most malignant astrocytic tumor (WHO grade IV). "Heterologous expression of GPR37L1-eYFP in either HEK293 or U87 glioblastoma cells yielded two cell surface species of approximately equivalent abundance, the larger of which is N-glycosylated at Asn105." (PMID 33203955, 2020). "Thus far, our evidence for proteolytic processing of the N-terminus has come from heterologously expressed GPR37L1-eYFP in FlpIN HEK293 or human glioblastoma cells." (PMID 33203955, 2020).
heart failure (2 papers, 2015 to 2018). Inability of the heart to pump blood at an adequate rate to meet tissue metabolic requirements. "GPR37L1 has been linked to the control of blood pressure in an exciting yet puzzling study of the genetic causes of human heart failure, where the authors performed microarray analysis on explants from 12 patients with heart failure, relative to two reference libraries." (PMID 26635605, 2015).
ischemia (2 papers, 2018 to 2022). A hypoperfusion of the BLOOD through an organ or tissue caused by a PATHOLOGIC CONSTRICTION or obstruction of its BLOOD VESSELS, or an absence of BLOOD CIRCULATION. "However, prosaposin expression and release are increased in ischemia and we found that expression of Gpr37l1 is increased in the penumbra of lesions caused by MCAO, so it is likely that glutamate transport activity is inhibited in these conditions." (PMID 28795439, 2018). "GPR37L1 can protect astrocytes against oxidative stress, and we show below that it also protects neurons in ischemia." (PMID 28795439, 2018). "Neuronal death was increased by ∼40% in Gpr37l1–/– brain compared to wild type in an in vitro model of ischemia." (PMID 28795439, 2018). "Such prolonged activation will occur during the prolonged elevation of extracellular glutamate concentration that occurs in ischemia and GPR37L1 should thus decrease the neurotoxic rise of [Ca2+]i that occurs in neurons in ischemia." (PMID 28795439, 2018). "The addition of prosaptide to boost GPR37L1 signaling significantly reduced cell death in the pyramidal layer of the hippocampus in Gpr37l1+/+ slices (a ∼25% decrease comparing cell death in ischemia with or without prosaptide, n = 4, p = 0.01)." (PMID 28795439, 2018). "The lack of a difference in glutamate transporter current with GPR37L1 knocked out could reflect GPR37L1 not being activated under physiological conditions, since it is known that the expression and release of prosaposin are up‐regulated following ischemia." (PMID 28795439, 2018). "However, GPR37L1‐mediated signalling inhibited astrocyte glutamate transporters and – surprisingly, given its lack of expression in neurons – reduced neuronal NMDA receptor (NMDAR) activity during prolonged activation of the receptors as occurs in ischemia." (PMID 28795439, 2018). "After chemical-induced ischemia, cultured hippocampal slices from mice lacking GPR37 L1 (Gpr37 l1-/-) displayed substantially increased neuronal death, suggesting that GPR37 L1 functions in a neuroprotective manner following ischemia ex vivo." (PMID 35409385, 2022).
ischemic stroke (2 papers, 2018 to 2022). A stroke disorder caused by obstruction of blood flow to the brain, due to thrombotic (local blood clot formation) or embolic (due to a blood clot or other material traveling from another site) event. "The focus of this review will thus be on the roles of two brain expressed orphan GPCRs, namely GPR37 and GPR37L1, in regulating various pathological processes underlying ischemic stroke." (PMID 35409385, 2022). "A drastic increase in neuronal loss after an ischemic stroke in GPR37L1 knockout mice further reinforces the importance of these receptors." (PMID 30260505, 2018). "Moreover, the deletion of GPR37L1 drastically increased the neuronal loss after an ischemic stroke." (PMID 30260505, 2018).
breast carcinoma (1 paper, 2025). "Therefore, the 3.7‐fold downregulation of Gpr37l1 in the hippocampus of CRSTumor mice may represent a novel drug target for neuroprotection and improving cognitive function in stressed patients diagnosed with breast cancer." (PMID 40172096, 2025).
diabetes (1 paper, 2024). "Furthermore, we found GPR37L1 downregulation not only in DRGs of mice with chemotherapy and diabetes, but also in DRGs of patients with painful diabetic neuropathy." (PMID 38530364, 2024). "To evaluate the contribution of GPR37L1 to neuropathic pain, we generated 2 animal models by systemic injection of streptozotoxin (STZ), a diabetes-inducing toxin, and paclitaxel (PTX), a chemotherapy drug." (PMID 38530364, 2024).
glioma (1 paper, 2022). A benign or malignant brain and spinal cord tumor that arises from glial cells (astrocytes, oligodendrocytes, ependymal cells). "Others were robust and shared across most samples such as CD74 receptor binding to MIF, COPA, or APP as cognate ligands and SPP1-CD44 (myeloid to glioma signaling) and TNFRSF1A-GRN, PGRMC2-CCL4L2, MDK-SORL1 or LRP1, and GPR37L1-PSAP (glioma to myeloid signaling)." (PMID 35140215, 2022).
left ventricular hypertrophy (1 paper, 2018). Enlargement of the LEFT VENTRICLE of the heart. "Moreover, a previous study reported that GPR37L1 knockout mice have left ventricular hypertrophy (LVH) and ~ 60 mmHg higher systolic BP than that of cardiac-specific, GPR37L1-overexpressing transgenic mice." (PMID 29625592, 2018).
neuropathy (1 paper, 2024). A disorder affecting the nervous system that manifests with pain, tingling, numbness, and/or muscle weakness. "Thus, GPR37L1 in SGCs offers a therapeutic target for the protection of neuropathy and chronic pain." (PMID 38530364, 2024). "We postulate that dysregulation of GPR37L1/KCNJ10 signaling in SGCs in neuropathy conditions (CIPN and DPN) will impair the SGC’s function of K+ buffering, leading to sequential increases in extracellular levels of K+, nociceptor excitability, and pain sensitivity." (PMID 38530364, 2024).
Obesity (1 paper, 2022). Accumulation of substantial excess body fat. "With the ultimate goal of assessing the viability of GPR37L1 as a clinical target for obesity, we sought to assess how the deletion of Gpr37l1 would affect the whole-body response to HFD challenge, which is known to increase markers of inflammation." (PMID 35681509, 2022). "Overall, these results indicate that while GPR37L1 may play a minor role in whole-body metabolism, it is not a viable clinical target for the treatment of obesity." (PMID 35681509, 2022).
Vestibular schwannoma (1 paper, 2025). A vestibular schwannoma (also known as acoustic neuroma, acoustic neurinoma, or acoustic neurilemoma) is a benign, usually slow-growing tumor that develops from the VIIIth cranial nerve supplying the inner ear. "Our cell communication analysis based on the curated receptor-ligand pair database showed that fibroblast in vestibular schwannoma microenvironment mainly regulated the biological behavior of tumor cells through PSAP/GPR37L1, MDK/(ITGA6 + ITGB1), IGF2/(ITGA6 + ) and MDK/LRP1 signaling axes." (PMID 40629113, 2025).
tumor (5 papers, 2021 to 2025). "The natural history analysis showed that the genetic ablation of Gpr37l1 results in the marked delay of post-natal tumor occurrence and the decreased incidence of more aggressive tumor types." (PMID 35457105, 2022). "The mitogenic ciliary functions of G-protein coupled receptor 37-like 1 (GPR37L1) in SHH–SMO signaling are particularly attractive to target cancer via the tumor microenvironment." (PMID 34436033, 2021). "Other membrane proteins, such as GPCRs (e.g., GRM6, GPR37L1, NMUR2), are highly expressed to mediate growth and survival signaling, amplify tumor proliferation signals, and prevent apoptosis." (PMID 41440381, 2025).
cardiovascular disease (3 papers, 2015 to 2020). "GPR37L1 is an orphan G protein-coupled receptor expressed exclusively in the brain and linked to seizures, neuroprotection and cardiovascular disease." (PMID 33203955, 2020). "Specifically, GPR37L1 was listed as being “downregulated” in cardiovascular disease, although no data was presented to support this claim and p > 0.005 for the failing vs. non-failing heart comparison of GPR37L1 gene expression." (PMID 26635605, 2015).
infection (1 paper, 2025). The state of being infected such as from the introduction of a foreign agent such as serum, vaccine, antigenic substance or organism. "Nine down-regulated DEGs were commonly downregulated in response to either Aβ pathology or MA10 infection (Vegfa, Atp1a2, Slc6a11, Gja1, Slc6a11, Gpr37l1, Plpp3, Gstm1, Agt)." (PMID 41497643, 2025).
neurological disorders (1 paper, 2022). "GPR37L1 is an orphan G-protein-coupled receptor, which is implicated in neurological disorders, but its normal physiological role is poorly understood." (PMID 36430766, 2022).
peripheral neuropathy (1 paper, 2024). A disorder affecting the peripheral nervous system. "Remarkably, MaR1 conferred protection against chemotherapy-induced peripheral neuropathy (CIPN) by inducing GPR37L1-dependent upregulation of surface KCNJ10 expression and KCNJ10-mediated K+ currents in SGCs." (PMID 38530364, 2024). "Peripheral neuropathy induced by streptozotoxin (STZ) and paclitaxel (PTX) led to reduced GPR37L1 expression on the plasma membrane in mouse and human DRGs." (PMID 38530364, 2024).
GPR37L1 also shares sentences with these, for which no sentence is quoted: Anxiety (2 papers); brain ischemia (1); cancer (1); cardiac hypertrophy (1); diabetic neuropathy (1); medulloblastoma (1); multiple sclerosis (1); myocardial infarction (1); Parkinsonism (1).